ALB (albumin)
Diseases named in the same sentence as ALB in open-access papers (continued):
Sharing a sentence is not in itself a finding about the gene and the disease.
Hypoalbuminemia (continued). "Patients with hypoalbuminemia had significantly higher mortality and composite event rates (death or readmission) compared with those with normal albumin levels." (PMID 41431585, 2025). "Serum biochemistry revealed improved hypoalbuminemia (3.0 g/dL) and hyperglobulinemia (5.1 g/dL) with an albumin-to-globulin ratio of 0.6." (PMID 40430745, 2025). "In severe pneumonia patients, inflammation and infection reduce albumin synthesis, increase its breakdown, and enhance vascular permeability, leading to hypoalbuminemia." (PMID 40938884, 2025). "In the same study, patients with initially low albumin levels who experienced normalization after device implantation had significantly better outcomes than those with persistent hypoalbuminemia during mechanical support." (PMID 41153732, 2025). "The risk of mortality in PLWHIV is 4.52 times higher for people with hypoalbuminemia than for those with serum albumin values ≥ 3.5 g/L10." (PMID 40898300, 2025). "The use of CPP, though non‐leukoreduced, in dogs was reported in a single previous study focused on its impact on albumin concentration and colloid osmotic pressure in critically ill dogs with hypoalbuminemia." (PMID 40521764, 2025). "During the disease course, the patient developed hypoalbuminemia (lowest serum albumin 19.5 g/L), persistent hypokalemia (lowest serum potassium 2.95 g/L), and transient urinary pH elevation to 7.5." (PMID 40826693, 2025). "In another prospective study of 576 hospitalized patients with heart failure, the 30-day mortality of 160 patients with hypoalbuminemia was 21.8%, which was 2.44 times greater than that of patients with a normal albumin concentration." (PMID 40705791, 2025). "Each 1 g/L increase in preoperative albumin reduced postoperative DVT risk by 8.8%, the cut-off value was 41.9 g/L, underscoring the clinical relevance of correcting preoperative hypoalbuminemia as a targeted preventive strategy." (PMID 40917834, 2025). "Given that hypoalbuminemia (albumin 2.63 g/dL [26.3 g/L]) was required for the diagnosis of PLE, significant multicollinearity was found between the group variable and albumin concentration." (PMID 40123416, 2025). "For instance, a recent prospective study of 386 trauma patients reported early-onset hypoalbuminemia (albumin < 3.5 g/dL) in 53.1% of cases within the first week." (PMID 41226896, 2025). "Mean preoperative albumin levels were 4.1 ± 0.5 g/dL, with 20 patients (14.3%) presenting hypoalbuminemia (Albumin < 3.4 g/dL)." (PMID 40507204, 2025). "Laboratory tests showed jaundice (total bilirubin 5.1 mg/dL), coagulopathy (prothrombin time-international normalized ratio 1.8), and hypoalbuminemia (albumin 2.7g/dL)." (PMID 40937155, 2025). "Concerning hypoalbuminemia, different criteria have been used in clinical studies (e.g., serum albumin level less than 2.5 g/dL or 3.2 g/dL)." (PMID 41301633, 2025). "Older age, previous antibiotic exposure within 90 days, and hypoalbuminemia (serum albumin <3 g/dL) emerged as significant predictors, with hypoalbuminemia demonstrating the strongest association (aOR 2.27)." (PMID 41439186, 2025). "NS is a common renal disease characterized by high proteinuria (urine protein > 3.5 g/d), hypoalbuminemia (serum albumin < 30 g/L), edema, and hyperlipidemia." (PMID 40190356, 2025). "A cohort study reported on the adverse effects of albumin supplementation in hypoalbuminemia, including traumatic brain injury related to intracranial pressure." (PMID 40649163, 2025). "Since albumin is synthesized in the liver, hypoalbuminemia is a direct consequence of hepatic dysfunction." (PMID 41428744, 2025). "Albumin levels <35 g/L are considered to be indicative of hypoalbuminemia, whereas those between 35 and 40 g/L are mildly reduced, and >40 g/L are normal." (PMID 40297171, 2025). "Based on established reference values, hypoalbuminemia (serum albumin < 3.5 g/dL) was identified in 42% (n=42) of the study participants." (PMID 41536368, 2025).
Hypoalbuminemia (continued). "In individuals receiving NOACs, elevated uric acid/albumin ratio, NLR, PLR, and SII scores, hypoalbuminemia, and hypolipidemia were significantly associated with bleeding risk." (PMID 41227038, 2025). "It is also worth noticing that high dose CsA can inhibit hepatic albumin synthesis, leading to hypoalbuminemia." (PMID 40051558, 2025). "The study suggests that FST without albumin supplementation can be effective in selected AKI patients with hypoalbuminemia, particularly those with higher baseline albumin levels and lower illness severity scores." (PMID 41291529, 2025). "A serum ALB level below 35 g/L is indicative of hypoalbuminemia, a frequent condition in hospitalized patients, particularly those critically ill." (PMID 40843069, 2025). "4.5% of recipients with normal albumin levels, 9% with mild, and 10% with moderate hypoalbuminemia group experienced DGF." (PMID 39906535, 2025). "This resulted in a final analytical sample of 20,725 patients, with 3661 (21.7%) having reported active smoking and 2037 (12.1%) having an albumin level below 3.5 g/dL (hypoalbuminemia)." (PMID 41527604, 2025). "The biochemistry analysis revealed mild hypoalbuminemia, as both albumin and total protein levels were slightly below normal." (PMID 40646741, 2025). "As a surrogate marker of nutritional status, albumin demonstrated a significant association with the development of CIN, with hypoalbuminemia identified as a risk factor for CIN." (PMID 41597302, 2025). "Background/Objectives: Albumin supplementation is widely used for hypoalbuminemia treatment in patients with critical illness, especially those with cirrhosis." (PMID 40649163, 2025). "We examined how albumin supplementation affects survival outcomes in patients with sepsis with hypoalbuminemia." (PMID 40649163, 2025). "Although the classical definition of hypoalbuminemia is <30 g/L, some studies have reported that serum total protein is <60 g/L or albumin is <35 g/L as hypoalbuminemia, because even mild hypoalbuminemia affects the outcome of patients." (PMID 41488107, 2025). "Patients in the ICU often exhibit hypoalbuminemia, a condition in which albumin is crucial as the main contributor of unmeasured anions within the body." (PMID 40680007, 2025). "Misclassification using the adjustment formulas was worse in the presence of hypoalbuminemia (albumin level <30 g/L)." (PMID 39836424, 2025). "Hypoalbuminemia during severe illness is often driven by inflammation, as inflammatory mediators suppress albumin synthesis in favor of producing other acute-phase proteins." (PMID 40649865, 2025). "The ALBIOS trial demonstrated that albumin administration reduces fluid balance and vasopressor dependency, with greater benefit in severe hypoalbuminemia." (PMID 40585555, 2025). "For hypoalbuminemia patients, carefully supplement albumin after assessing serum albumin and hemodynamics, adjust diet to high—calorie, vitamin—rich, sodium—controlled meals, and use enteral or parenteral nutrition if digestion is impaired." (PMID 40104144, 2025). "Lower baseline albumin was associated with increased 90-day mortality, consistent with prior PEG literature, where hypoalbuminemia is a well-known marker of poor prognosis after PEG." (PMID 41303753, 2025). "Beyond its classical role as a marker of hypoalbuminemia, ALB has recently emerged as an active mediator of immune dysregulation." (PMID 40640102, 2025). "Among the systemic disturbances observed after trauma and TBI, derangements in serum protein homeostasis, particularly hypoalbuminemia (low albumin levels) of total serum protein content, account for approximately 80% of the plasma oncotic pressure." (PMID 41226896, 2025). "In this retrospective cohort of 925 patients with severe TBI, we observed a pronounced shift in serum albumin from predominantly normo- to hypoalbuminemia on admission to marked hyperalbuminemia at ICU discharge." (PMID 41226896, 2025).
Hypoalbuminemia (continued). "Hypoalbuminemia markedly reduces the binding rate of drugs to ALB, thereby increasing their apparent volume of distribution (Vd) and clearance (CL)." (PMID 41424785, 2025). "The dramatic rise in ALBs observed during ICU care indicates that modern critical care interventions (e.g., intravenous albumin administration, concentrated feeding, or hemoconcentration via diuresis) can effectively reverse initial hypoalbuminemia." (PMID 41226896, 2025). "A major concern for HDx is that the loss of dialysate albumin is greater than that of the HDF, possibly resulting in transient hypoalbuminemia." (PMID 41200111, 2025). "Furosemide and spironolactone are the first-line diuretics, and albumin infusion is recommended for hypoalbuminemia." (PMID 40417670, 2025). "Based on our review, 42% of our patients who developed IIE had hypoalbuminemia, supporting the need for routine testing of albumin levels and the administration of albumin infusions to patients with low albumin levels." (PMID 40647490, 2025). "When albumin levels are low (hypoalbuminemia), the secretion of diuretic agents into the tubular lumen can be diminished." (PMID 40279952, 2025). "From this dataset, 1,147,433 patients who developed sepsis and hypoalbuminemia with albumin levels <3.5 g/dL were identified." (PMID 40649163, 2025). "Research has shown that hypoalbuminemia is associated with long-term adverse outcomes in ESRD patients, and those with low serum albumin levels face an increased mortality risk." (PMID 41586234, 2025). "The secondary objective was to evaluate improvements in serum albumin levels among patients presenting with hypoalbuminemia." (PMID 41003011, 2025). "In this case, we present a 3-year-old male patient with severe symptoms due to hypoalbuminemia, such as testicular swelling and frequent albumin infusion." (PMID 41209104, 2025). "Currently, there is no universally established normal range for serum albumin levels in preterm infants; however, moderate hypoalbuminemia is commonly defined as plasma albumin concentration below 25 g/L, and severe hypoalbuminemia as below 20 g/L." (PMID 41574353, 2025). "Particular diagnostic significance lies in the identification of hyperglobulinaemia accompanied by hypoalbuminaemia or low-to-normal serum albumin." (PMID 41142566, 2025). "Among the four dogs, one dog had hypoalbuminemia and three had a normal pre-treatment serum albumin concentration." (PMID 38595652, 2024). "This phenomenon is opposite to the effect of hypoalbuminemia on the concentration of certain antibiotics (such as ceftriaxone); that is, the lower the albumin level, the more free drug and the higher the clearance rate of ceftriaxone." (PMID 39734407, 2024). "Patients with hypoalbuminemia had a higher mean age (59.62 ± 18.552) compared to those with normal albumin levels (53.54 ± 18.646) (P = 0.003)." (PMID 39048942, 2024). "Hypoalbuminemia affects drug metabolism, antioxidant defense, and toxin processing because albumin is the primary transport protein in blood plasma." (PMID 38777824, 2024). "The analysis of PFS was only near-significant in this cohort (HR = 1.66, 95% CI 0.962–2.86; Cox P = 0.0685), although patients with hypoalbuminemia had a median of 4 months, while patients with normal albumin had a median PFS of 8 months." (PMID 38755213, 2024). "Serum albumin levels are also a key indicator of the body’s nutritional status, and hypoalbuminemia is a key predictor of death in patients with CKD." (PMID 39507908, 2024). "Among patients with persistent SIRS after 48 h, 70.8% had hypoalbuminemia, and 29.2% had normal albumin levels (P < 0.001)." (PMID 39048942, 2024). "The study population was divided into two groups based on preoperative serum albumin: normal albumin (≥ 3.5 g/dL) and hypoalbuminemia (< 3.5 g/dL)." (PMID 38972926, 2024). "The ICU physician administered 600 mL of fresh frozen plasma to correct the coagulation issue and continued to infuse albumin to address the hypoalbuminemia." (PMID 39654230, 2024).
Hypoalbuminemia (continued). "The reason for this is that hypoalbuminemia can reduce the binding of albumin to tigecycline, leading to an increase in free drug concentration and an apparent increase in the volume of distribution." (PMID 38218863, 2024). "Adults had a higher incidence of hypoalbuminemia (31.6% vs 11.1%, p = 0.009), but the albumin levels were only marginally lower." (PMID 38439032, 2024). "Hypoalbuminaemia has long been recognized as a feature of cancer cachexia, and it is therefore expected that albumin was the most frequently used biomarker (29/52 trials), likely due to its dual role as a marker of inflammation and nutrition." (PMID 38783477, 2024). "Most patients undergoing ERCP have ongoing acute inflammatory processes potentially leading to hypoalbuminemia secondary to an increased capillary permeability and consequent extravasation of serum albumin into the interstitial space." (PMID 39859962, 2024). "66.7% of patients with a BISAP score ≥ 3 had hypoalbuminemia compared to 33.3% with normal albumin levels (P < 0.001)." (PMID 39048942, 2024). "Hypoalbuminemia was present among 119 (59.20%) patients while 82 (40.80%) patients had normal albumin levels." (PMID 39539863, 2024). "Given that albumin levels at the time of diagnosis can vary significantly depending on age and regional disease patterns, assessing the degree of hypoalbuminemia is crucial for mortality prediction in these patients." (PMID 39246646, 2024). "Warfarin exposure decreases albumin levels and hypoalbuminemia leads to increase in the free fraction of warfarin." (PMID 38440292, 2024). "Specifically, the incidence of hypoalbuminaemia (defined as an albumin concentration <3.5 g/dL) was 58.4% (472/808) in the MIMIC-IV cohort and 74.1% (519/700) in the eICU-CRD cohort." (PMID 39357986, 2024). "It is also recommended to correlate zinc levels with CRP and albumin levels and to use caution when diagnosing zinc deficiency in the background of high CRP >20 mg/L, hypoalbuminemia, or anemia." (PMID 38975455, 2024). "Patients with hypoalbuminemia had a median OS of 7 months, whereas those with normal albumin had a median OS of 20 months." (PMID 38755213, 2024). "The use of hyperoncotic albumin in normovolemia management is further supported by evidence suggesting that hypoalbuminemia moderates the volume expansion effect of albumin." (PMID 39336939, 2024). "Blood profiles revealed mild anemia, lymphopenia, thrombocytopenia, hypoalbuminemia, hyperglobulinemia, and an albumin to globulin ratio of 0.4." (PMID 38680809, 2024). "Hypoalbuminemia (≤ 30 g/L) was observed in 124 patients (33.4% of cases), and these patients had a higher mean age compared to those with normal albumin levels (P = 0.003)." (PMID 39048942, 2024). "In a multivariable logistic regression analysis, patients with hypoalbuminemia had an adjusted OR of 2.99 (95%CI: 2.14–4.18) compared to those with normal albumin levels (≥ 35 g/L)." (PMID 38420358, 2024). "The PNI, derived from serum albumin and lymphocyte counts, can decrease due to hypoalbuminemia or lymphocytopenia." (PMID 38473396, 2024). "The mean creatinine level was 12.5 mg/l ± 19.333 in patients with hypoalbuminemia compared to 7.5 mg/l ± 4.298 in those with normal albumin levels (P = 0.006)." (PMID 39048942, 2024). "Li+sick dogs presenting hypoalbuminemia showed higher MLR ratios (P = 0.001) than those with normal albumin values." (PMID 39444011, 2024). "Mean preoperative albumin levels were 3.6 ± 0.4 g/dL, with 46 patients (37.1%) presenting hypoalbuminemia (Albumin < 3.4 g/dL)." (PMID 39519455, 2024). "Most patients (n=101, 74.8%) had average serum albumin levels, and 25.2% (n=34) showed hypoalbuminemia." (PMID 39698191, 2024). "Hypoalbuminemia is currently defined as serum albumin ≤35 g/L and occurs prevalently in old population or in patients with frailty or affected by liver or renal disease or chronic inflammation." (PMID 39010980, 2024).
Hypoalbuminemia (continued). "Yet, reduced levels of albumin in serum (hypoalbuminemia, <30 g·L−1) during illnesses can indicate many diseases." (PMID 38785712, 2024). "In a previous study, cats presenting with hypoalbuminemia at diagnosis had a more than 3‐fold longer ST (684 days) than cats with normal albumin concentration (214 days)." (PMID 38517293, 2024). "A study has reported that post-surgical patients often experience hypoalbuminemia, with 56.4% having albumin levels under 3.5 g/dL and 20.6% under 3.0 g/dL within the first seven days after surgery." (PMID 39457184, 2024). "The upregulation of CRP production is invariably accompanied by a rapid decrease in blood albumin levels, leading to hypoalbuminemia." (PMID 39064000, 2024). "Overall, the serum albumin level increased and the prevalence of hypoalbuminemia decreased as the BMI was higher—from 50.6% in underweight patients to 23.4% in those with class 3 obesity (p for trend < 0.001)." (PMID 39728268, 2024). "Hypoalbuminemia (serum albumin <35 g/L) was observed in 44.9% of patients, and lymphocytopenia (ALC <1.0 × 109/L) in 29.9%." (PMID 39882120, 2024). "In our study, the NAFLD population showed either hyperalbuminemia or hypoalbuminemia compared to the “normal” population at different albumin reference values." (PMID 38505748, 2024). "A T-test between albumin level classification and the length of hospital stay showed a significant difference between the means of length of hospital stay between patients with a normal albumin level and those with hypoalbuminemia." (PMID 38707022, 2024). "Albumin has been recognized as a biomarker for critical illness, and hypoalbuminemia in sepsis is related to a bad prognosis." (PMID 38326383, 2024). "Patients also had significant hypoalbuminemia, with an average albumin level of 29.06 g/L in the combined group and 30.27 g/L in the sequential group." (PMID 39635590, 2024). "The identification of hypoalbuminemia as a predictor of mortality underscores the importance of routine assessment of serum albumin levels in healthcare settings, particularly within this age group." (PMID 39010980, 2024). "Our study examined the long-term mortality effect of admission-time hypoalbuminemia, defined as a serum albumin level of <3.5 g/dL, according to BMI range among 6283 AMI survivors." (PMID 39728268, 2024). "The patient's clinical course underscored the limitations of relying solely on total protein excretion as a diagnostic criterion for nephrotic syndrome, especially in cases where significant hypoalbuminemia affects the urinary albumin excretion rate." (PMID 39131015, 2024). "When categorized into two groups, the hypoalbuminemia group had an OR of 2.99 (95% CI: 2.14–4.18, p < 0.001) compared to the normal albumin level group." (PMID 38420358, 2024). "Another important component of the HALP score, albumin, particularly hypoalbuminemia, plays a significant role in predicting mortality in acute ischemic stroke." (PMID 39347246, 2024). "striata extract was reported to contain high albumin (2.17 ± 0.14 g), zinc (3.34 ± 0.8 mg), and iron (0.20 ± 0.09 mg), which is sufficient to provide albumin for highly demanded such as hypoalbuminemia and growing children." (PMID 38777845, 2024). "Platelet counts averaged 310 × 109/L, & the mean serum albumin level is 2.6 ± 0.7 g/dL, indicative of hypoalbuminemia in many cases." (PMID 39803050, 2024). "The incidence of 30-day readmission was significantly higher among hypoalbuminemia patients than those with normal albumin levels (OR = 2.090, 95%CI:1.296–3.370, p = 0.003)." (PMID 38528491, 2024). "The paucity of available data on serum albumin levels in the case reports and case series included in our systematic review made it difficult to evaluate the prevalence of hypoalbuminemia among patients with ertapenem neurotoxicity." (PMID 38715573, 2024). "Among patients with recorded serum albumin levels (n=21), hypoalbuminemia was recorded in 12 (57.1%)." (PMID 38846234, 2024).